ENSG00000258461 (novel transcript)
Gene: Protein-coding gene on chromosome 15 (42,348,103 to 42,412,317, forward strand). Ensembl gene ENSG00000258461.
Genetic constraint (gnomAD): Missense variants: 86 observed, 87.17 expected, observed/expected ratio (o/e) 0.99, 90% interval 0.83 to 1.18. Synonymous variants: 21 observed, 31.93 expected, observed/expected ratio (o/e) 0.66, 90% interval 0.47 to 0.95.